CTLA4 (cytotoxic T-lymphocyte associated protein 4)
Diseases named in the same sentence as CTLA4 in open-access papers (continued):
Sharing a sentence is not in itself a finding about the gene and the disease.
metastatic melanoma (continued). "Combination of CTLA-4 and PD-1 blockers was then evaluated to increase the response rates in patients, and ipilimumab (anti-CTLA-4) plus nivolumab (anti-PD-1) combination was shown to significantly enhance efficacy in metastatic melanoma patients." (PMID 31196207, 2019). "Ipilimumab, an anti-CTLA4 monoclonal antibody can elicit an objective response in 10%-15% of metastatic melanoma patients." (PMID 35582715, 2019). "Anti-CTLA-4 (ipilimumab) and anti-PD-1 (nivolumab and pembrolizumab) combination was studied extensively in metastatic melanoma patients and the efficacy of the combination was demonstrated in multiple clinical trials." (PMID 31196207, 2019). "With respect to the clinical application, chemotherapy using dacarbazine combined with anti-CTLA-4 was first tested in patients with metastatic melanoma." (PMID 29482595, 2018). "Immune checkpoint inhibition (ICI) with anti-CTLA-4 and/or anti-PD-1 antibodies is standard treatment for metastatic melanoma." (PMID 30002656, 2018). "More importantly, a trial combining the DNMTi SGI­100 (also known as guadecitabine) with CTLA4 blockade (ipilimumab) is recruiting patients with metastatic melanoma (NCT02608437)." (PMID 29482595, 2018). "Recently, two studies using oncolytic T-Vec in metastatic melanoma patients have demonstrated promising response rates when administered in combination with CTLA-4 or PD-1 blockade." (PMID 29983890, 2018). "Combination immunotherapy with blockade of CTLA-4 and PD-1 is approved for metastatic melanoma and is under investigation in several other indications." (PMID 29789020, 2018). "CTLA-4 was also the first checkpoint molecule to be targeted in human cancer using mAbs, ipilimumab and tremelimumab, in advanced metastatic malignant melanoma." (PMID 29868474, 2018). "Ipilimumab (CTLA-4 blocker) regulates T cell activation and improves survivability of metastatic melanoma patients." (PMID 29872383, 2018). "As part of the evaluation of 8C3 mAb as a potential RIT agent, we performed its side by side comparison with one of the standards of care drugs for metastatic melanoma treatment – anti-CTLA4 mAb." (PMID 29615812, 2018). "The combination of ACT and anti-CTLA-4 is currently underway in a phase II study in patients with metastatic melanoma (NCT02027935)." (PMID 29482595, 2018). "Ipilimumab is an FDA-approved anti-CTLA-4 monoclonal antibody used in treatment of metastatic melanoma." (PMID 29382383, 2018). "Inhibitory monoclonal antibodies against the CTLA‐4 and PD‐1 immune checkpoint receptors significantly improved the survival of metastatic melanoma patients, including patients with MBM." (PMID 30133176, 2018). "Case 2: A patient with metastatic melanoma was treated with anti-CTLA-4 + PD-1 therapy and achieved a major partial response for a total of nineteen months." (PMID 30400822, 2018). "The augmentation of eosinophil count (>100/mm3) and of ALC (>1000/mm3) in the circulation after the first infusion of anti-CTLA-4 mAb showed correlation with improved overall survival (OS) in a retrospective analysis of N = 77 metastatic melanoma patients." (PMID 30004433, 2018). "Further, in the diffuse B16F10 murine model of metastatic melanoma, selective blockade had reduced the number of tumor lesions comparably with conventional anti-CTLA-4 antibody treatment." (PMID 30319637, 2018). "Ipilumumab, a monoclonal antibody against cytotoxic T lymphocyte antigen 4 (CTLA4), was approved in March 2011 and was the first immune checkpoint inhibitor to show an overall survival advantage in metastatic melanoma." (PMID 29507655, 2018).
metastatic melanoma (continued). "Firstly, ipilimumab—a fully humanized monoclonal antibody blocking the co-inhibitory molecule cytotoxic T-lymphocyte antigen 4 (CTLA4)—proved to be effective in patients with metastatic melanoma at the dose of 3 mg/kg q3w." (PMID 29642948, 2018). "In 2011, the US Food and Drug Administration (FDA) approved ipilimumab, an antibody that targets CTLA-4, for metastatic melanoma, making it the first FDA-approved ICB therapy for treatment of solid tumors." (PMID 30497521, 2018). "Recent data suggest that patients experiencing grade ≥ 3 irEC on the CTLA-4 and PD-1 combination for the treatment of metastatic melanoma can safely resume PD-1 alone upon disease progression." (PMID 30577825, 2018). "The first of such agent approved by the FDA to treat patients with metastatic melanoma was ipilimumab, a CTLA-4 inhibitor that was approved for clinical use in early 2011, and since, several reports of abscopal effect have emerged." (PMID 29719740, 2018). "Despite this fact, anti-PD-1/anti-CTLA-4 combination therapy is being used a first-line treatment for previously untreated patients with metastatic melanoma." (PMID 29725606, 2018). "In this phase I study, patients with histologically confirmed stage III/IV metastatic melanoma received IL BCG injection followed by up to four cycles of intravenous ipilimumab (anti-CTLA-4) (ClinicalTrials.gov number NCT01838200)." (PMID 29552014, 2018). "Checkpoint inhibitors of programmed cell death 1 (PD-1) and its ligands (PD-L1 and PD-L2) and cytotoxic lymphocyte antigen protein 4 (CTLA-4) are an emerging class of agents currently licensed in metastatic melanoma, NSCLC and Hodgkin’s lymphoma." (PMID 30326612, 2018). "Ipilimumab, a monoclonal anti-CTLA-4 antibody, was the first checkpoint inhibitor to demonstrate an improved overall survival rate in patients with previously treated metastatic melanoma." (PMID 29725606, 2018). "For example, retrospective data indicate that metastatic melanoma patients who suffered from a serious anti-CTLA-4-related adverse event (defined as grade 3–4 and/or requiring systemic immunosuppression) were able to be safely started on an anti-PD-1 agent." (PMID 30228268, 2018). "In the pursuit of finding biomarkers that predict treatment response, we evaluated the association between serum biomarkers of collagen and vimentin turnover and outcomes in metastatic melanoma patients treated with the anti-CTLA-4 antibody ipilimumab (IPI)." (PMID 30567561, 2018). "The administration of mAbs targeting immune checkpoint molecules such as Cytotoxic T Lymphocyte Antigen-4 (CTLA-4) and Programmed Death-1 (PD-1) significantly increases overall survival (OS) of metastatic melanoma patients." (PMID 29290886, 2017). "It was reported that CTLA-4 blockade induces tumor regression in several murine model and in patients with metastatic melanoma in clinical trial." (PMID 28333940, 2017). "Association of CTLA-4 −1577G>A and CT60G>A SNV genotypes with best overall response to ipilimumab in metastatic melanoma patients estimated through a multinomial logistic regression modeling." (PMID 28446908, 2017). "In 2010, ipilimumab, a human monoclonal antibody that blocks CTLA-4, was demonstrated to improve overall survival in patients with metastatic melanoma." (PMID 29211042, 2017). "A recent study evaluating potential biomarkers for response to treatment was conducted in metastatic melanoma patients treated with anti-CTLA-4 followed by anti-PD-1 therapy, using tumor biopsies at specific time points before and during treatment." (PMID 29088901, 2017).
metastatic melanoma (continued). "Immunotherapies, like T cell checkpoint blockade with anti-CTLA-4 and anti-PD-1antibodies, have improved the median survival of patients with metastatic melanoma and brain melanoma." (PMID 29129918, 2017). "This synergy is currently under investigation in prospective clinical trials, especially to evaluate abscopal responses following RT in patients with metastatic melanoma treated with ipilimumab (therapy with CTLA-4 blockade)." (PMID 28222111, 2017). "Ipilimumab (Yervoy, Bristol-Myers Squibb), a fully human immunoglobulin G1 (IgG1), targeting CTLA-4, was the first mAb to demonstrate a survival benefit in patients with metastatic melanoma." (PMID 29290886, 2017). "Preliminary results from the simultaneous blockade of PD1 and CTLA4 in metastatic melanoma were also published, and now this combination is being tested in many different neoplasms." (PMID 28881701, 2017). "Further development of checkpoint inhibitors directed against CTLA-4 and PD-1 have demonstrated impressive clinical outcomes in the treatment of metastatic melanoma." (PMID 28434398, 2017). "The introduction of targeted therapies including BRAF and MEK inhibitors as well as CTLA-4 and PD-1 axis targeting immune checkpoint inhibitors have dramatically improved the treatment and prognosis of patients with extracranial metastatic melanoma." (PMID 28374234, 2017). "Blocking antibodies for this pathway, such as anti-CTLA-4 or anti-PD-1 mAb, lead to remarkable outcome in advanced stages of diseases and achieve response rates of up to 30% in metastatic melanoma patients that have failed standard treatments." (PMID 28123870, 2016). "In 2015, these studies led to the accelerated approval of anti-CTLA-4 (ipilimumab) in combination with anti-PD-1 (nivolumab) for the treatment of unresectable or metastatic melanoma in the USA." (PMID 27847783, 2016). "Here, a patient with metastatic melanoma pretreated with ipilimumab, an anti-CTLA-4 blocking antibody, was vaccinated with IDO-silenced DCs cotransfected with mRNA for survivin or hTERT tumour antigens." (PMID 27504122, 2016). "Nevertheless, the combination of MEK inhibitors (trametinib), BRAFV600E inhibitors (dabrafenib), and anti-CTLA-4 (ipilimumab) resulted in severe gastrointestinal toxicity in patients with metastatic melanoma in a phase I/II study." (PMID 27847783, 2016). "Metastatic melanoma is the most common primary diagnosis under study, and majority of studies are evaluating RT and CTLA-4 blockade administered in concurrent fashion." (PMID 27660705, 2016). "One antibody targeting CTLA-4, ipilimumab (Yervoy, Bristol Myers Squibb), is approved for metastatic melanoma." (PMID 27660705, 2016). "The PTML was first determined for a cohort of metastatic melanoma patients (n = 76) treated with the FDA-approved immunotherapy ipilimumab (anti-CTLA-4)." (PMID 27776519, 2016). "This approach has recently shown efficacy in a phase I clinical trial together with anti-CTLA4 antibody Ipilimumab in patients with metastatic melanoma (NCT02073123)." (PMID 28123870, 2016). "Ipilimumab is a human monoclonal antibody that blocks CTLA-4 and was considered as the first option for advanced metastatic melanoma based on phase II and III trials." (PMID 27764796, 2016). "Currently, the combination of ACT and anti-CTLA-4 is studied in a phase II study in patients with metastatic melanoma (NCT02027935)." (PMID 27847783, 2016). "Cytotoxic T-lymphocyte antigen-4 (CTLA-4) blockade via the monoclonal antibody ipilimumab also has attracted attention due to positive results in patients with metastatic melanoma and renal cell carcinoma, as well as several other malignancies." (PMID 26807740, 2016). "In particular, ipilimumab, which blocks CTLA-4, has improved overall survival in patients with metastatic melanoma." (PMID 26901565, 2016). "With respect to the clinical application, chemotherapy (dacarbazine) combined with anti-CTLA-4 (ipilimumab) was first tested in metastatic melanoma patients." (PMID 27847783, 2016).
metastatic melanoma (continued). "In contrast, results of the phase 3 study (MDX010–20) leading to the approval of ipilimumab (anti-CTLA4) for the treatment of metastatic melanoma demonstrated clinical response rate in 11% (CR – 1.5%; PR – 9.5%) of patients, with DC rate of 28.5%." (PMID 26020391, 2015). "Antibodies targeting CTLA4 and PD-1/PD-L1 have shown remarkable clinical efficacy in metastatic melanoma." (PMID 25854582, 2015). "Of special note are recent studies showing that targeting both PD-1 and CTLA-4 together in patients with metastatic melanoma resulted in higher rates of objective response and significantly longer progression-free survival than targeting CTLA-1 alone." (PMID 26460952, 2015). "In contrast, a clinical benefit has been observed in patients with metastatic melanoma using antibodies against CTLA4, which globally increase the number of circulating CD8 + T cells irrespective of antigen specificity." (PMID 26048402, 2015). "Patient was treated with radiation therapy session followed by cycles of ipilimumab, known to be an antibody to immune check point molecule CTLA4, which is used in metastatic malignant melanoma." (PMID 25705230, 2015). "The modern generation of immunotherapy, including CTLA4 and PD-1 antagonists, has enabled us to make clinical achievements and prolong the life of patients with metastatic melanoma." (PMID 26124920, 2015). "The B16 model was used to help demonstrate the efficacy of anti-CTLA4 therapy, a drug that has revolutionized the treatment of metastatic melanoma in humans." (PMID 26048402, 2015). "Ipilimumab is a first-in-class immunological checkpoint blockade agent and monoclonal antibody against Cytotoxic T-Lymphocyte Antigen 4 (CTLA-4) that has demonstrated survival benefit and durable responses in patients with metastatic melanoma." (PMID 26082835, 2015). "Examples are ipilimumab, a mAb directed against the receptor cytotoxic T lymphocyte-associated antigen 4 (CTLA-4), or pembrolizumab (MK-3475), a mAb against the programed cell death protein-1 (PD-1), used for the treatment of metastatic melanomas." (PMID 25688243, 2015). "Among 198 patients with metastatic melanoma and renal cancer treated with anti-CTLA-4, 21% experienced Grade 3/4 colitis, and the mortality in patients who developed autoimmune colitis due to bowel perforation was about 5%." (PMID 24594636, 2014). "For example, ipilimumab which binds to CTLA-4, has been shown to result in 2-year survival rates of 23.5 % in patients with metastatic melanoma." (PMID 24816725, 2014). "In particular, ipilimumab, a human monoclonal antibody that blocks cytotoxic T lymphocyte-associated antigen 4 (CTLA-4), has been associated with improved survival in patients with metastatic melanoma." (PMID 25609545, 2014). "In 2011, two agents, ipilimumab (a fully human monoclonal antibody that blocks CTLA-4 to promote antitumor immunity) and vemurafenib (a potent inhibitor of mutated V600E BRAF) were approved in Europe and the US for the treatment of metastatic melanoma." (PMID 25502446, 2014). "Blockade of CTLA-4 has yielded increased T-cell mediated anti-tumor responses, most notably in metastatic melanoma." (PMID 25355407, 2014). "There is therefore a strong rationale for using anti-CTLA-4 therapy to treat elderly patients with metastatic melanoma in order to enhance adaptive immunity against this disease." (PMID 24708900, 2014). "Anti-CTLA4 antibodies such as ipilimumab are immune modulatory biologics and are regarded as a milestone in the treatment of metastatic melanoma." (PMID 25254213, 2014). "Ipilimumab, a cytotoxic T-lymphocyte antigen-4 (CTLA-4) binding agent, has proven to be an effective monotherapy for metastatic melanoma and has shown antitumor activity in trials when administered with other therapeutic agents." (PMID 23873089, 2013).
metastatic melanoma (continued). "Ipilimumab, an antibody that blocks cytotoxic T-lymphocyte antigen-4 (CTLA-4), an inhibitory molecule present on activated T cells, is used to treat patients with metastatic melanoma." (PMID 24216706, 2013). "Ipilimumab, a CTLA-4 antagonist, has been shown to improve the median survival of patients with metastatic melanoma." (PMID 24383025, 2013). "For example, mAbs to CTLA4 have antitumor efficacy with prolonged overall survival in patients with metastatic melanoma, and an anti-CTLA4 mAb is clinically approved by the FDA." (PMID 24367702, 2013). "Ipilimumab, an anti-CTLA-4 monoclonal antibody, has been shown to improve overall survival in patients with metastatic melanoma." (PMID 23497384, 2013). "The first of these agents approved by the FDA is ipilimumab (Bristol-Myers Squibb, New York, NY, USA), a monoclonal antibody against the inhibitory receptor cytotoxic T-lymphocyte antigen-4 (CTLA-4), for metastatic melanoma." (PMID 24829752, 2013). "Ipilimumab is the first-in-class anti-CTLA-4 therapy to be approved by the FDA for treatment of metastatic melanoma and has demonstrated efficacy in these patients." (PMID 23738073, 2013). "Ipilimumab, a cytotoxic T-lymphocyte antigen-4 (CTLA-4) blocking antibody, has been approved for the treatment of metastatic melanoma and induces adverse events (AE) in up to 64% of patients." (PMID 23341990, 2013). "A large phase III trial in metastatic melanoma comparing anti-CTLA-4 plus DTIC versus DTIC alone found a survival benefit for the combination therapy compared to DTIC chemotherapy alone." (PMID 23626745, 2013). "In 2011, the U.S. Food and Drug Administration approved ipilimumab (Yervoy, Bristol-Myers Squibb, Princeton, NJ, USA), a CTLA-4 antagonist, for the treatment of metastatic melanoma after it was shown to improve median overall survival." (PMID 24383025, 2013). "The FDA recently approved an anti-CTLA-4 antibody (Iplimumab) for the treatment of metastatic melanoma." (PMID 23557194, 2013). "The blocking of CTLA-4 using human monoclonal antibodies, such as Ipilimumab, is currently used to relieve CTLA-4-mediated inhibition of anti-tumor immune response in metastatic melanoma." (PMID 23634660, 2013). "Objective tumor responses were noted in 11% of evaluable patients with metastatic melanoma, which is also consistent with the prior experience with CTLA4 antagonistic antibodies." (PMID 23171508, 2012). "CTLA4 has become a validated target for therapy in patients with metastatic melanoma based on the survival advantage in two phase 3 clinical trials using the CTLA4 blocking fully human IgG1 antibody ipilimumab (formerly MDX010)." (PMID 23171508, 2012). "CTLA4 blocking monoclonal antibodies provide a low frequency but durable tumor responses in patients with metastatic melanoma, which led to the regulatory approval of ipilimumab based on two randomized clinical trials with overall survival advantage." (PMID 23171508, 2012). "Good news included the approval of anti-CTLA-4 as a therapy for metastatic melanoma in April and the announcement in early October of the Nobel Prize in Physiology and Medicine awarded to pioneering studies in the field of immunology." (PMID 22620286, 2012). "In fact, the use of a blocking antibody to CTLA-4 (Ipilumimab) in metastatic melanoma patients demonstrated clinical efficacy and was recently given approval by the FDA." (PMID 22485134, 2012). "In metastatic melanoma new treatment options have recently emerged targeting BRAF or CTLA-4 showing improved overall survival, but these treatments are associated with significant toxicities and costs." (PMID 22719881, 2012). "The administration of the CTLA4-blocking antibody tremelimumab to patients with metastatic melanoma influences signaling networks downstream of the TCR and cytokine receptors both in T cells and monocytes." (PMID 20856802, 2010).